ARHGAP27 (Rho GTPase activating protein 27)
Description:
Rho GTPase-activating protein which may be involved in clathrin-mediated endocytosis. GTPase activators for the Rho-type GTPases act by converting them to an inactive GDP-bound state. Has activity toward CDC42 and RAC1 (By similarity).
Synonyms: CAMGAP1; SH3D20; PP905; FLJ43547; SH3P20
Tractability: Small molecule: it has a binding pocket of medium quality. Antibody: UniProt places it where antibodies can reach, with medium confidence; its Gene Ontology location is reachable by antibodies, with medium confidence. PROTAC: ubiquitination databases record sites on it; its protein half-life has been measured.
Gene: Protein-coding gene on chromosome 17 (45,393,898 to 45,434,421, reverse strand). Ensembl gene ENSG00000159314.
Subcellular location: Cytoplasm; Membrane
Subcellular location (Human Protein Atlas): Cytosol; Nucleoplasm
Pathways (Reactome):
Signal Transduction: CDC42 GTPase cycle; RAC1 GTPase cycle
Gene Ontology:
Molecular function: GTPase activator activity; SH3 domain binding; actin filament binding
Biological process: receptor-mediated endocytosis; regulation of small GTPase mediated signal transduction; Rho protein signal transduction; small GTPase-mediated signal transduction; signal transduction
Cellular component: cytoplasm; cytosol; plasma membrane; membrane
Genetic constraint (gnomAD): Loss-of-function variants: 49 observed, 87.64 expected, observed/expected ratio (o/e) 0.56, 90% interval 0.44 to 0.71. The upper end of that interval is the gene's LOEUF score, 0.71, which puts it in group 2 of 6, group 1 being the genes least tolerant of losing a copy. Missense variants: 1,109 observed, 1,097.3 expected, observed/expected ratio (o/e) 1.01, 90% interval 0.96 to 1.06. Synonymous variants: 519 observed, 474.03 expected, observed/expected ratio (o/e) 1.09, 90% interval 1.02 to 1.18.
Homologues: Orthologues: chimpanzee ARHGAP27 (99% identical), macaque ARHGAP27 (97% identical), pig ARHGAP27 (84% identical), rat Arhgap27 (83% identical), mouse Arhgap27 (82% identical), rabbit ARHGAP27 (82% identical), dog ARHGAP27 (69% identical), guinea pig ARHGAP27 (67% identical), tropical clawed frog arhgap27 (45% identical), zebrafish arhgap27l (39% identical), zebrafish arhgap27 (37% identical), Caenorhabditis elegans tag-325 (20% identical), and 1 more. Paralogues in human: ARHGAP12 (34% identical), ARHGAP9 (25% identical), ARHGAP15 (22% identical).
Diseases named in the same sentence as ARHGAP27 in open-access papers:
ARHGAP27 is named in the same sentence as 13 diseases in open-access papers, as found by Europe PMC text mining. Sharing a sentence is not in itself a finding about the gene and the disease. The quoted sentences say what the papers report.
COVID-19 (2 papers, 2023 to 2024). A disease caused by infection with severe acute respiratory syndrome coronavirus 2. "Finally, a high-impact variant never before associated with COVID-19 was also identified in the ARHGAP27 gene (rs201721078)." (PMID 38543725, 2024). "Therefore, the objective of our study is to investigate genetic variants in the genes AQP3, ARHGAP27, ELF5, IFNAR2, LIMD1, OAS1 and UPK1A, which were selected due to the association of these genes with the severity of COVID-19, in a sample of Amazonian indigenous peoples." (PMID 38543725, 2024). "Seven new genes (AQP3, ARHGAP27, ELF5, IFNAR2, LIMD1, OAS1 and UPK1A) were related to the severity of COVID-19 in populations of European origin." (PMID 38543725, 2024). "Another study developed in 34 Spanish hospitals with 11,939 positive cases of COVID-19 identified the relationship of the AQP3, ARHGAP27, ELF5, IFNAR2, LIMD1, OAS1 and UPK1A genes with the severity of the disease." (PMID 38543725, 2024).
pancreatic cancer (2 papers, 2021). "Furthermore, Smad3's β4 region-dependent downregulation of ARHGAP24 and ARHGAP27 was also observed in PANC-1 human pancreatic cancer cells." (PMID 33741342, 2021). "As ARHGAP27 mRNA is expressed in pancreatic cancer, we speculate that rs147904962 mediates regulation of cancer-associated ARHGAP27, promoting carcinogenesis through dysregulation of Rho/Rac/Cdc42-like GTPases." (PMID 34926279, 2021).
Parkinson’s (2 papers, 2023 to 2025). "Dementia-related genes ARHGAP27, CYP1B1, KANSL1, KRTCAP2, LSM7, and GBA are also linked to altered behavior, neurodegeneration, inflammation, and Parkinson’s." (PMID 37588516, 2023).
schizophrenia (2 papers, 2023 to 2025). A major psychotic disorder characterized by abnormalities in the perception or expression of reality. "Disease-risk genes that overlapped across PD, ALS and schizophrenia were KANSL1-AS1 (microglia and oligodendrocytes) and KANSL1, ARHGAP27, and PLEKHM1 (microglia)." (PMID 40202986, 2025).
anxiety disorder (1 paper, 2024). A category of psychiatric disorders which are characterized by anxious feelings or fear often accompanied by physical symptoms associated with anxiety. "Specifically, ARHGAP27, which encodes for a Rho GTPase activating protein involved in cytoskeletal remodeling and cellular motility, has been implicated in various neurological conditions and anxiety disorders." (PMID 39514479, 2024).
chronic lymphocytic leukemia (1 paper, 2020). "The evidence for ARHGAP27 is weak (mRNA expression in chronic lymphocytic leukemia), but the ARHGAP gene family has been linked to carcinogenesis through the dysregulation of Rho/Rac/Cdc42-like GTPases27." (PMID 32612205, 2020).
idiopathic intracranial hypertension (1 paper, 2025). "For peripheral blood cells, we found upregulation of ARHGAP27 (Rho GTPase-activating protein 27) in CD4+ and CD8+ lymphocytes in MS patients compared to negative controls (idiopathic intracranial hypertension patients)." (PMID 40242760, 2025).
tumor (2 papers, 2024). "A significant association was detected between ARHGAP21, ARHGAP26, ARHGAP27, ARHGAP 34, ARHGAP 35, ARHGAP42, and ARHGAP46 and the tumor stages." (PMID 38783033, 2024). "Through an extensive review, we found that ARHGAP27 and ARHGAP44 are hardly relevant in tumour research." (PMID 39075640, 2024).
ARHGAP27 also shares sentences with these, for which no sentence is quoted: cancer (1 paper); dementia (1); dermatitis (1); eczema (1); ovarian carcinoma (1).